CXCL9 (C-X-C motif chemokine ligand 9)
Diseases named in the same sentence as CXCL9 in open-access papers (continued):
Sharing a sentence is not in itself a finding about the gene and the disease.
cancer (continued). "On the other hand the serum levels of ADIPOQ, CXCL9, PECAM-1, Prolactin, sVEGFR-1 and sVEGFR-2 in the T2D-HCC patients were higher than those of patients with only T2D while they were similar to those of HCC patients, confirming that these proteins are specific for the cancer presence." (PMID 26226632, 2015). "Among them, interferon (IFN) inducible CXC chemokine, CXCL9 (Mig), CXCL10 (IP-10) and CXCL11 (I-TAC), are multifunctional chemokine orchestrating immunity and angiogenesis via shared G-protein coupled receptor CXCR3, thus, these ligands might play a crucial role in cancer." (PMID 26910919, 2016). "A study has indicated that macrophage polarity, defined by the expression of CXCL9 and SPP1 rather than traditional M1 and M2 markers, controls human cancers." (PMID 40416872, 2025). "Reduced levels of CXCL9 and CXCL10 are correlated with the immunosuppressive microenvironment, negative responses to ICIs, and poor prognosis among cancer patients." (PMID 34855841, 2021). "Differential expression analysis between ER+ and ER– cancers identified over-expression of TTF1, LAF-4 and C-MYB (p ≤ 0.05), and between pCR vs non-pCRs, over-expression of CXCL9, AREG, B-MYB and under-expression of ABCG2." (PMID 28697743, 2017). "PTGS2, FN1, CXCL9, CXCL10, ZIC2 e OVOL1 podem desempenhar alguns papéis no carcinoma nasofaríngeo." (PMID 27765529, 2017). "Furthermore, a recent study redefines macrophage polarity on the basis of their expression of CXCL9 and SPP1, as opposed to traditional “M1” and “M2” markers, with this signature displaying prognostic significance across multiple cancer types." (PMID 39165364, 2024). "Additionally, an analysis of COAD and adjacent non-cancerous tissue samples from the TCGA database confirmed significant increases in CXCL1, CXCL8, CXCL9, and CXCL11 in cancer tissues, while CCL22 showed no significant change." (PMID 38791448, 2024). "ZIC2 e OVOL1 podem funcionar no carcinoma nasofaríngeo almejando-se de maneira significativa os genes suprarregulados (como o PTGS2, FN1, CXCL9 e CXCL10) na rede reguladora de fator de transcrição - genes diferencialmente expressos (p.ex., ZIC2→PTGS2 e OVOL1→CXCL10)." (PMID 27765529, 2017). "When the cells were treated with a combination of cetuximab and MEK or JNK, the expression levels of CCL5, CXCL9 and CXCL10 increased, confirming that not one but multiple pathways downstream of the EGFR act in concert to block IFNγ/TNFα -induced chemokine expression by these cancer cell lines." (PMID 30192802, 2018).
bacterial infection (16 papers, 2009 to 2025). "Bacterial infection of ductal cells also coincides with the fact that CXCL9, CXCL10, CXCL12, chemokines involved in lymphocyte trafficking, are predominantly expressed in the ductal epithelium adjacent to lymphoid infiltrates in SS." (PMID 32208441, 2020). "CXCL9 concentrations for viral, fungal/mycobacterial and bacterial infections were: 6278 (p=0.004), 1940 (p=0.016) and 1359 (p=0.004), respectively (p-values indicate comparison with healthy samples)." (PMID 31414076, 2018). "Chemokine ligand 9 (CXCL9) is thought to aid in the infiltration and retention of activated T-cells in response to bacterial infection and will give an indication of the direct response to the bacterial infection." (PMID 38879567, 2024). "In particular, we identified that gut F. nucleatum was positively associated with several serum proteomic markers which might be involved in host inflammation and immune activation related to bacterial infection (e.g., CXCL9, TNFRSF9)." (PMID 37237391, 2023). "BMMs that are mobilized in response to bacterial infections within peripheral tissues are known to be potent inducers of pro‐inflammatory interferons (eg, IFNγ), as well as additional cytokines and chemokines such as IL‐1, IL‐18, Ccl3, Cxcl9, and others." (PMID 32841534, 2020). "CXCL9 may be of particular importance in promoting host defense against bacterial infection as it is strongly induced in several murine models of pulmonary infection including Klebsiella pneumoniae and Mycobacterium tuberculosis." (PMID 21124994, 2010). "Among these, GBP2, CXCL9, and IRG1 represent some of the pathways involved in the protective response: GBP2, a member of the GTPase family, drives macrophages toward an inflammatory state while combating bacterial infection through vacuole disruption and pyroptosis induction." (PMID 39819562, 2025).
inflammation (15 papers, 2019 to 2025). Aberrant reaction of the microcirculation characterized by movement of fluid and leukocytes from the blood into extravascular tissues. "However, while Il6 (interleukin-6) was unaltered, a reduced expression of Il1b (interleukin-1beta), a master pro-inflammatory cytokine in joint inflammation, was significantly reduced in the OA knees of Cxcl9-deficient mice 4 weeks after ACLT." (PMID 40047894, 2025). "Altogether these analyses indicate that the CXCL9–11/CXCR3 receptor ligand axis plays an important role in HDV-mediated liver inflammation." (PMID 39980752, 2025). "Consistent with liver inflammation, the serum levels of pro-inflammatory proteins, including CCL2, CXCL9, IL-17a, IL-17f, and TNF receptor superfamily member 12a, were increased in HF-HC-fed mice." (PMID 41362710, 2025). "Chemokine ligand 9 (CXCL9) is a small cytokine belonging to the CXC chemokine family, which is induced by inflammatory responses and is also known to be induced by pulmonary inflammation." (PMID 32718325, 2020). "In particular, the serum CXCL9 and CXCL10 levels in our patients showed correlations with BALF levels so that these serum chemokines may reflect not only systemic inflammation but also local pulmonary inflammation." (PMID 33137121, 2020).
cardiovascular diseases (10 papers, 2019 to 2025). "Elevated circulating CXCL9 has been observed in patients with cardiovascular disease, in ostensibly healthy older adults, and in association with frailty and mortality risk." (PMID 41419927, 2025). "CXCL9 is increasingly recognized as a key contributor to age-related immune activation, cardiovascular disease, and cellular senescence." (PMID 41419927, 2025). "Considering that miR-6089 in RA patients had an inverse and significant correlation with DAS-28, NT-proBNP and CXCL9, it can be assumed that miR-6089 plays a role in the preventing the pathological events of cardiovascular disorders in RA patients." (PMID 39281435, 2024). "Regarding its anti-inflammatory effects, miR-6089 may play an important role in preventing the pathological events of cardiovascular disorders in RA patients, through its inhibitory effects on inflammatory chemokines, such as CXCL9, and NT-ProBNP." (PMID 39281435, 2024).
adenocarcinoma (5 papers, 2019 to 2025). A common cancer characterized by the presence of malignant glandular cells. "Additionally, in comparison with normal samples, the expression level of CCR7, CXCL10, IDO1, and MMP9 were increased in phases of adenocarcinoma’s tissue, while the expression level of CXCL9 and VCAM1 were decreased." (PMID 31214045, 2019). "In agreement with studies carried out in adenocarcinoma cell lines, we found similar upregulation of genes such as IDO1, GBP1, CXCL9, CXCL10, and CXCL11 in response to IFN-γ, all of which are also known to be upregulated in IBD patients." (PMID 33396621, 2020).
kidney diseases (5 papers, 2012 to 2024). "Non-invasive biomarkers of renal disease such as chemokines (e.g., CXCL9, CXCL10) and donor-derived cell-free DNA are increasingly being considered to improve diagnosis and predict allograft rejection." (PMID 38916313, 2024). "High expressions of chemokines and their receptors in the infiltrating immune cells are recognized as the characteristic events in the progression of DN and CXCR3, and its ligands, CXCL9, CXCL10, and CXCL10 are the well-known risk factors for inflammatory-based kidney diseases." (PMID 36686486, 2022). "CXCL9 levels were 5.5-fold higher in those with AIN than in individuals in the control group and between AIN and various other kidney diseases." (PMID 37395276, 2023). "CXCR3 mediates kidney disease in murine lupus nephritis, and reduction of the transcription factor FLI1 results in amelioration of kidney disease in MRL/lpr mice with concomitant reduction in CXCR3+ T cells and CXCL9/10 expression." (PMID 29568300, 2018).
respiratory diseases (5 papers, 2023 to 2025). "CXCL9, CCL2, IL6, CXCL10, and IL8 have been linked to various respiratory diseases and retain sensitivity for their level estimates as well." (PMID 40650062, 2025). "In multiple animal models of respiratory diseases, the treatment with XC221GI led to controlling the levels of CXCL9, CXCL10, CXCL11, IL-6 and IL-8, and to decrease of extent of the pathogen-driven cytokine storm." (PMID 37214455, 2023).
infectious disease (3 papers, 2015 to 2017). A disorder directly resulting from the presence and activity of a microbial, viral, or parasitic agent in humans. "In fact, both CXCL9 rs10336 TT and CXCL10 rs3921 GG genotypes have also been related to higher cellular expression of CXCL9 and CXCL10 in other infectious disease, such as Chagas infection, where they were also related to a higher severity of chronic Chagas cardiomyopathy." (PMID 28755163, 2017).
neurological disease (3 papers, 2021 to 2025). "Ligands of the CXCR3 receptor include CXCL9, CXCL10, and CXCL11, exhibit varied roles across different neurological disorders." (PMID 40781073, 2025). "To rule out the possibility that patients without focal CNS lesions harbor elevated CXCL13 or CXCL9 CSF levels, we also used archived CSF samples from 101 patients with various non-lesional neurological diseases as historical controls (for diagnoses)." (PMID 33841320, 2021).
cardiac disease (2 papers, 2021 to 2023). "CXCL9 has already been proven as a viable biomarker in cardiac disease, bolstering the case for its use in a predictive cSDH model." (PMID 36974123, 2023).
colon (2 papers, 2022 to 2025). "The current research on gastrointestinal tumors has further validated the critical role of the IFN-γ/STAT1/JAK/CXCL chemokine pathway—particularly involving CXCL9 and CXCL10—in promoting antitumor immune responses." (PMID 40909948, 2025). "Should this regulation be confirmed, the underlying reasons for the observed disparities in the effects of CXCL9 across various gastrointestinal tumors warrant further exploration." (PMID 40909948, 2025).
immune diseases (2 papers, 2012 to 2023). "Particularly, CXCL9, CXCL10, and CXCL11 in cluster 7 were closely associated with disease progression and immune disorders, irrespective of whether the patients had been treated with ART." (PMID 36408648, 2023). "Some IRPs in cluster 7, such as CXCL11, CXCL9, TNF, CXCL10, and IL18, are closely associated with HIV-1 disease progression and immune disorders, irrespective of whether patients received ART treatment." (PMID 36408648, 2023).
central nervous system diseases (1 paper, 2022). "Two of them are Cxcl9 and Cxcl11, which are involved in Th1-type response, correlating with T-cell infiltration; the comprehension of CXCR3 (C-X-C Motif Chemokine Receptor 3)/CXCL9′s binding mechanism of action is considered crucial for the treatment of central nervous system diseases." (PMID 35806178, 2022).
vasculopathy (1 paper, 2022). "Histological analysis of affected tissues from mice treated with SSc PBMCs (SSc hu-mice) demonstrated substantial inflammation, fibrosis and vasculopathy with human immune cell infiltration and increased expression of IL-17, TGF-β, CCL2, CCL3, and CXCL9." (PMID 36175484, 2022).
CXCL9 also shares sentences with these, for which no sentence is quoted: acute respiratory distress syndrome (5 papers); lupus nephritis (5); oral squamous cell carcinoma (5); ulcerative colitis (5); visceral leishmaniasis (5); atopic dermatitis (4); Hemophagocytosis (4); Splenomegaly (4); Addison’s disease (3); bacteremia (3); cholangiocarcinoma (3); chronic GVHD (3); dermatomyositis (3); infarction (3); metastatic disease (3); pancreatic adenocarcinoma (3); pancreatitis (3); schizophrenia (3); thyroiditis (3); allergies (2); Anxiety (2); basal cell carcinoma (2); Chronic colitis (2); chronic kidney disease (2); chronic obstructive pulmonary disease (2); emphysema (2); fungal infection (2); gastritis (2); Graves disease (2); hypothyroidism (2).
A further 162 diseases each share a sentence with CXCL9 in 2 papers or fewer.